ICAM1 (intercellular adhesion molecule 1)
Diseases named in the same sentence as ICAM1 in open-access papers (continued):
Sharing a sentence is not in itself a finding about the gene and the disease.
Sepsis (continued). "We determined the protein expression of ICAM-1 and VCAM-1 and their immunoreactivity in liver and lung tissues from an experimental CLP sepsis mice model with and without GdCl3 pretreatment to compare the effects of GdCl3 on these tissues." (PMID 38254684, 2024). "The qPCR results showed that kaempferol inhibited significantly the mRNA level of ICAM-1 compared with saline-treated CLP group at 24 h, but there were no significant changes of MCP-1 and VCAM-1 in sepsis." (PMID 37440431, 2023). "Using a mouse model of CLP‐induced sepsis, ICAM‐1+ neutrophils were found to be expanded in the blood and lungs of WT mice, but not in CIRP KO mice after sepsis." (PMID 34953031, 2022). "However, how Kupffer cell activation affects adhesion molecules (ICAM-1 and VCAM-1) in sepsis has not been determined." (PMID 38254684, 2024). "Furthermore, the tempting sequential concept of Ang-2 as a primer for excess endothelial adhesion molecule (e.g. ICAM-1, VCAM-1, and E-selectin) expression in sepsis has not been investigated in human sepsis." (PMID 19416526, 2009). "She reported that applied OMVs from sepsis sepsis-inducing bacteria in contrast to non-sepsis sepsis-inducing bacteria significantly reduced the activity of RNase1 and promoted endothelial cell activation, as indicated by increased IL-8, CXCL10, ICAM-1, and IL-1β expression." (PMID 39697663, 2021).
melanoma (167 papers, 1999 to 2025). A malignant, usually aggressive tumor composed of atypical, neoplastic melanocytes. "Neutralisation of IL-8 reduces extravasation of PMN-associated tumour cells, whereas ICAM-1 overexpression provides an alternative pathway for melanoma extravasation." (PMID 41451221, 2025). "In malignant melanoma, the primary and metastatic tumor control were affected by the loss of L-Selectin and/or ICAM-1 on tumor cells." (PMID 40071851, 2025). "For instance, CD44 and ICAM1 are key adhesion molecules implicated in tumor cell migration, metastasis, and modulation of the immune response, with ICAM1 upregulation on melanoma cells and exosomes linked to enhanced metastatic potential and immune escape." (PMID 40805206, 2025). "ICAM-1 on melanoma, breast, lung and colorectal cancer cells is associated with malignancy and involved in tumour initiation, progression and metastasis." (PMID 38391953, 2024). "The predictive model created in this work comprises five inflammatory response-related genes: C3AR1, CXCL10, EIF2AK2, EMP3, and ICAM1, all of which are all overexpressed in melanoma tissue and are associated with a poor prognosis." (PMID 35982458, 2022). "It has been demonstrated that human primary melanoma cells (T1) produce high levels of ICAM1, and that increased ICAM1 expression associated with PI3K/AKT pathway activation can be exploited by metastatic melanoma cells to resist CTL-mediated lysis." (PMID 35982458, 2022). "All of the melanoma lines that express ICAM-1 also proved to be susceptible to infection with CVA21." (PMID 34503272, 2021). "Transduction of YUMM 2.1 mouse melanoma cells with human ICAM-1 rendered them susceptible to viral infection and cell death, however, viral spread appears to occur more slowly in these cells." (PMID 34503272, 2021). "The level of ICAM-1 expression on melanoma cells correlates with tumor thickness and risk of metastases." (PMID 29245925, 2017). "Induction of ICAM1 in resistant melanoma cells is sufficient to restore the susceptibility of tumor cells to the CTL-mediated death." (PMID 26338962, 2015). "ICAM1 overexpression causes phosphorylation and internalization of VE-cadherin, resulting in blood vessel permeabilization, potentially explaining why old age is associated with poor melanoma outcome." (PMID 38760832, 2024). "Interestingly, metastatic melanoma cells escape CTL-mediated killing by shifting the ICAM-1 expression, which in turn has been associated with activation of the PI3K/AKT-driven signaling contributing to resistance to apoptosis signals." (PMID 39596815, 2024). "In addition, an increase in serum levels of soluble ICAM-1 (sICAM-1) has been associated with disease progression, tumor aggressiveness and decreased survival in several malignancies such as melanoma, chronic B-lymphocytic leukemia, lymphoma, and CRC." (PMID 31231358, 2019). "In melanoma and gastric cancer, ICAM1 expression was associated with an increase in metastases." (PMID 28105922, 2016). "This view is further corroborated by animal studies that determined a 2.6-fold greater tumor volume in ICAM-1-deficient mice than in wild-type mice 14 days after injection of melanoma cells or a development of malignant tumors in LFA-1-deficient but not wild-type mice injected with cancer cells." (PMID 26513172, 2015). "Therefore, we hypothesize that mutations in CX3CL1 may also impact the function of ICAM-1, thereby influencing melanoma cell proliferation, invasion, and angiogenesis; however further in vitro experiments are required." (PMID 37875556, 2023). "Also ICAM-1 expression has been associated with the malignant potential of tumor cells and has thus been associated with metastases and poor prognosis in several cancers including melanoma, breast, lung and oral cancer." (PMID 31231358, 2019).
melanoma (continued). "Similarly, IgSF members such as L1CAM (CD171), NCAM (CD56), PECAM-1 (CD31), ALCAM (CD166), and ICAM-1 (CD54) have been associated with metastatic progression in a range of cancers including melanoma, glioma, breast, ovarian, endometrial, prostate, and colon cancer." (PMID 22272201, 2012). "Next, we stratified the TCGA SCKM patient cohort according to ICAM-1 expression level on melanoma cells and compared the highest (ICAM-1high) with the lowest (ICAM-1low) quartiles." (PMID 39867570, 2025). "IL-10 can inhibit essential steps in immune detection by decreasing the cell surface expression of HLA class I and II antigens and the intercellular adhesion molecule-1 (ICAM-1) in melanoma cells." (PMID 39187677, 2025). "ICAM-1 on melanoma cells and β2 integrin on neutrophils interacted, promoting anchoring to vascular endothelium in melanoma." (PMID 40564191, 2025). "Studies have shown that the interaction between β2 integrin on neutrophils and ICAM-1 on melanoma cells facilitates the anchoring of melanoma cells to the vascular endothelium." (PMID 40076927, 2025). "In murine melanoma models, IL-8-induced binding of neutrophil surface integrin β2 to tumor cell ICAM-1 stabilizes circulating tumor cells and potentiates their pulmonary dissemination." (PMID 40564191, 2025). "To this aim, we analyzed the relationship between ICAM-1 expression in the TCGA melanoma samples and several immune response gene signatures." (PMID 39867570, 2025). "This supports previous reports of VEGF reduction of TNF-α-induced upregulation of ICAM-1 and VCAM-1 in cultured ECs and tumour-associated ECs isolated from melanoma tissues." (PMID 40650058, 2025). "Cancers such as breast, multiple myeloma, and melanoma often upregulate ICAM-1 and DAF, which can be exploited by coxsackievirus strains like coxsackievirus A21 (CAVATAK)." (PMID 41294877, 2025). "By analyzing The Cancer Genome Atlas melanoma dataset, we further propose ICAM-1 upregulation on melanoma cells as a biomarker of a proinflammatory and antitumorigenic signature." (PMID 39867570, 2025). "A flow migration assay demonstrated that LFA-1 on human neutrophils initially captures ICAM-1 on both melanoma cells and the endothelium, whereas neutrophil Mac-1 binding to ICAM-1 stabilizes the aggregation." (PMID 39653768, 2025). "In cancer, ICAM1 overexpression has been proved in several types of tumors, including melanoma, breast, colorectal, and, lung cancer." (PMID 39820173, 2025). "Particularly, ICAM-1 upregulation on melanoma cells positively correlated with increased density of CD8+ T cell and other immune cells and with an IFN-γ gene signature predictive for improved response to therapy." (PMID 39867570, 2025). "ICAM-1 was markedly overexpressed in melanoma-derived exosomes, implicating it in the facilitation of tumor-associated intercellular adhesion and metastatic dissemination." (PMID 40805206, 2025). "B7-H3 (CD276), MIC-1, and ICAM1, however, were detectable and present in all three melanoma exosomes." (PMID 40805206, 2025). "Numerous studies tried to delineate the implications of melanoma ICAM-1 expression on its progression." (PMID 39867570, 2025). "A recent study described that elevated ICAM1 mRNA levels correlated with significantly improved survival in patients with stage III/IV melanoma." (PMID 39867570, 2025). "Our data support the superiority of DNMTi over other epigenetic inhibitors in reshaping a selection of surfaceome markers of advanced melanoma cells, specifically by inducing ICAM-1 upregulation." (PMID 39867570, 2025). "Coxsackievirus A21, an RNA virus that targets intercellular adhesion molecule-1 (ICAM-1) was studied for the treatment of advanced melanoma in combination with immunotherapy." (PMID 38399429, 2024). "The expression of ICAM1 in TCGA melanoma patients was significantly high than normal controls (t = ‐39.681; p < 0.001)." (PMID 38874532, 2024).
melanoma (continued). "These in vivo results support that ICAM1‐ADC monotherapy has potent anti‐melanoma activity for melanoma." (PMID 38874532, 2024). "There was a positive correlation between the mRNA levels of ICAM1 and the presence of BRAF mutations, which are among the most common genetic alterations in melanoma (r = 0.23, p < 0.001)." (PMID 38874532, 2024). "The opposite dependence between ICAM-1 expression and invasiveness was described for melanoma, in which the presence of this receptor on tumor cells is associated with lower aggressiveness and a higher patient survival rate." (PMID 39335111, 2024). "The IF staining images intuitively validated that PE‐conjugated ICAM1 antibodies initially bound on cytoplasmic membrane of melanoma cells and then were gradually internalized with incubation time." (PMID 38874532, 2024). "Taken together, this study queried the single‐agent efficacy of two different ICAM1‐ADCs in preclinical models of melanoma." (PMID 38874532, 2024). "In TCGA melanoma cohort, the prognosis of high‐ICAM1 expression group was significantly worse than low‐ICAM1 expression group (low‐ICAM1 group vs. high ICAM1 group: hazard ratio 0.61, p < 0.001; log‐rank p < 0.001)." (PMID 38874532, 2024). "ICAM-1 is upregulated in human melanoma cells during their metastasis from the primary tumour site to lymph nodes." (PMID 38391953, 2024). "To evaluate the in vivo efficacy of ICAM1‐ADCs, we first established a melanoma patient‐derived xenograft (PDX) model." (PMID 38874532, 2024). "Under shear flow, sFn and Fg enhance polymorphonuclear neutrophil (PMN)-mediated melanoma adhesion to the endothelium via ICAM-1." (PMID 37046617, 2023). "These EVs induced the activation of ERK and nuclear factor κB (NF-κB), and expression of intracellular adhesion molecule (ICAM-1) in lymphatic endothelial cells, thus enhancing lymphangiogenesis and melanoma cell adhesion." (PMID 36674479, 2023). "Fibrinogen (Fg) and soluble fibrin (sFn), ligands for integrin αvβ3 and ICAM-1, respectively, are expressed in melanoma and epithelial tumor cells." (PMID 37046617, 2023). "ICAM‐1 exhibits upregulated expression in malignant conditions, potentially participating in tumorigenesis and promoting the metastatic ability of melanoma, breast, gastric, pancreatic and lung cancers." (PMID 37082943, 2023). "The Fos and Jun family members bind to the AP‐1 recognizing sites on the ICAM‐1 promoter in homodimer or heterodimer forms, resulting in the transcription of AP‐1 responsive genes, which are highly expressed and active in melanoma cells." (PMID 37082943, 2023). "ICAM-1–αLβ2 interaction was also shown to play a role in the transendothelial migration of the melanoma." (PMID 36132127, 2022). "ICAM1 can also regulate immune cell-mediated tumor cytotoxicity, thereby improving the prognosis of patients with certain tumors, such as melanoma and oral squamous cell carcinoma." (PMID 36353618, 2022). "It was demonstrated that the coculture of melanoma cells with endothelial cells induced the expression of αLβ2 in melanoma cells, allowing them to interact with ICAM-1 in endothelial cells." (PMID 36132127, 2022). "ICAM1 has been proposed as a novel target for a range of solid tumors in recent years, including melanoma and mesenchymal thyroid carcinoma (ATC), and has significant research potential." (PMID 35982458, 2022). "Overexpression of ADAR1 induced ICAM1 expression and blocking of ICAM1 reduced the functions of ADAR1 killing melanoma cells." (PMID 34827646, 2021). "Taken as a whole, these data demonstrate that CVA21 can infect and kill melanoma cells that express ICAM-1." (PMID 34503272, 2021). "ICAM-1 (ICAM1) is physiologically present in low levels on leukocytes and endothelial cells, as well as melanoma cells, and levels can increase upon cytokine stimulation, e.g., with tumour necrosis factor (TNF) and interleukin (IL)-1." (PMID 34439879, 2021).
melanoma (continued). "CVA21 is an oncolytic virus naturally targeted to human ICAM-1 on the cell surface that can infect and kill melanoma cells." (PMID 34503272, 2021). "Multiple studies have identified the ability of α-MSH to reduce the expression of adhesion molecules linked to the metastatic potential of melanoma cells including ICAM-1 induced in melanoma cells by TNF-α." (PMID 34068618, 2021). "Melanoma and other malignant cells often exhibit impaired antiviral defenses and those expressing high levels of ICAM-1 can be efficiently infected and lysed by the virus, resulting in tumor destruction accompanied by innate and adaptive immune responses." (PMID 34503272, 2021). "Another study on melanoma patients pinpointed that lymphatic exudates contained enriched EVs with tumor-specific markers like tetraspanins, ICAM-1, Rab-GTPases and integrins." (PMID 31820036, 2020). "In particular, ICAM-1 upregulation is required to initiate the lymphatic spread of melanoma while different cathepsins have been demonstrated to be up-regulated in most primary melanomas and all cutaneous melanoma metastases." (PMID 33371199, 2020). "Attracted by IL-8 secreted by melanoma, neutrophils interacted with the melanoma cells through β2-integrin ICAM-1 and promoted docking along vascular endothelium." (PMID 33343560, 2020). "ADAR1, in an editing-independent manner, has been shown to transcriptionally regulate the biogenesis of miR-222 and thereby Intercellular Adhesion Molecule 1 (ICAM1) expression, which consequently affects melanoma immune resistance." (PMID 32650588, 2020). "As a ligand of β2 integrin, ICAM-1 binds to β2 integrin, thereby forming a complex between melanoma cells and neutrophils, which enhances melanoma adhesion to and migration through vascular endothelial cells." (PMID 33042821, 2020). "ILC2 trafficking is regulated by β2 integrin expression in the context of the inflammatory milieu, raising the possibility that high ICAM-1 expression on the lung and liver endothelium favors the recruitment of ILCs during melanoma metastasis." (PMID 33138017, 2020). "Besides their immunological role in the metastatic progression of melanoma to the liver, inflammatory cytokines have also been implicated in the adhesion of circulating murine melanoma cells to the hepatic microvasculature through ICAM-1 and VCAM-1 adhesion molecules." (PMID 33138017, 2020). "Further, activated T cells formed intra-tumoral clusters mediated by LFA-1/ICAM-1 interactions in mouse models of melanoma and breast cancer and similar T cell clusters were also visible in primary human melanoma." (PMID 31231358, 2019). "A similar biphasic response was observed for melanocytes and melanoma cells: Cytokine-induced ICAM-1 synthesis was inhibited within the first 16 hours and increased between 48 and 96 hours after UV-B treatment." (PMID 31882818, 2019). "Melanoma cells bind to ß2-integrins on polymorphonuclear neutrophils (PMN) via ICAM-1, whereas PMN themselves bind to ICAM-1 present on the endothelium." (PMID 30657059, 2019). "Potential oncolysis of a panel of six melanoma cell lines was inferred by increased levels of ICAM-1 and DAF." (PMID 31100962, 2019). "For example, in a mouse model of melanoma, NKp46+ innate lymphoid cells (ILCs) upregulate vascular adhesions such as ICAM1 and VCAM1, which facilitate the infiltration of additional immune cells with anti-tumor functions." (PMID 31497019, 2019). "Correlation between levels of cell adhesion molecules (ICAM-1, E-selectin, P-selectin) and T cell infiltration levels has also been shown in melanoma, glioblastoma, Merkel cell carcinoma and squamous cell carcinoma (SCC)." (PMID 31231358, 2019). "Most studies of T cell homing to tumors have focussed on the recruitment of effector T cells into B16 melanomas and shown important roles for P/E-selectin and ICAM-1 on tumor blood vessels as well as CXCR3 ligands." (PMID 31249570, 2019).